INS (insulin)
Diseases named in the same sentence as INS in open-access papers (continued):
Sharing a sentence is not in itself a finding about the gene and the disease.
diabetes (continued). "The pathophysiology of type 2 diabetes mellitus (T2D) is collectively governed by several factors, with peripheral insulin resistance and pancreatic β cell dysfunction being the central aspects." (PMID 41012462, 2025). "Insulin deficiency in diabetes can result in hypertriglyceridemia (HTG), as insulin is an anti-lipolytic agent and regulator of lipoprotein lipase (LPL) enzyme actions." (PMID 40612706, 2025). "Other baseline characteristics, including duration of diabetes and proportion of patients receiving insulin therapy and other medications, were comparable between groups." (PMID 41461045, 2025). "Our findings are in line with those studies since we identified the following potential biomarkers for early GDM prediction: history of high glucose level/diabetes, Insulin, Cholesterol, and LDL-C." (PMID 40082942, 2025). "Diabetes mellitus is characterized by high blood sugar levels due to insufficient insulin production or ineffective insulin response." (PMID 40283996, 2025). "Diabetes mellitus (DM) is a persistent disease characterized by elevated blood sugar levels and occurs from an imbalance in the secretion of insulin, insulin activity, or both." (PMID 41011204, 2025). "Serine protease Dipeptidyl peptidase-4 (DPP4) is an important therapeutic target for managing diabetes since it is essential to metabolising insulin and glucose." (PMID 40063647, 2025). "Typically, a nurse initiated action by calling a PGY1/2 to write or alter one or more prescriptions for insulin, ‘review’ or ‘sort out’ a patient’s diabetes, correct an unduly high or low blood glucose level, or start insulin." (PMID 40973362, 2025). "Upon adjustment, SAT density was associated with diabetes status and HbA1c, whereas VAT density was associated with fasting insulin level and HOMA-IR score." (PMID 40533477, 2025). "Diabetes care was frequently cited: continuous blood glucose monitoring allows acute therapy adjustments and holds potential for automated long-term insulin regulation (F1)." (PMID 41393840, 2025). "Clinically, individuals with a longer duration of diabetes, those living with obesity (BMI ≥30), patients dependent on insulin therapy, and those with comorbid conditions like hypertension and dyslipidemia were more likely to exhibit poor glycemic control." (PMID 40385776, 2025). "In the subgroup of patients with T2D, associations between AL and demographic or clinical characteristics were explored, including sex, age, diabetes duration, insulin use, diabetic macular edema, and retinopathy stage." (PMID 41356947, 2025). "Insulin, a peptide hormone crucial for diabetes management, necessitates strict storage (2-8oC) to maintain concentration, as per regulatory guidelines (e.g., USP, WHO)." (PMID 40465749, 2025). "Oxidative stress can worsen diabetes and its complications by impairing insulin secretion and increasing insulin resistance." (PMID 40766758, 2025). "In pancreatic islet tissues, mutants of the circadian gene CLOCK and the protein BMAL1 show significantly impaired glucose tolerance, decreased insulin secretion, and pancreatic β-cell defects, leading to the onset of diabetes." (PMID 40115347, 2025). "2-(3-Hydroxyphytanyl)-3-phytanyl-sn-glycerol in glycerolipids (GLs) belongs to the glycerol diester group; it can lower blood glucose, improve insulin sensitivity, and slow the process of diabetes; therefore, its content in D-W is much lower." (PMID 40076655, 2025). "Murine systems, though widely used in obesity and diabetes research, exhibit fundamental differences in lipid handling, insulin sensitivity, and immune responses compared to humans." (PMID 40141314, 2025). "In terms of diabetes management, metformin was the most used medication (64.5%), followed by insulin injections (52.6%), while the use of complementary medicine was relatively low (10.1%)." (PMID 41010974, 2025).
diabetes (continued). "More representative models have thus shifted toward diet-induced approaches that better recapitulate the gradual progression from insulin-sensitive to insulin-resistant phenotypes and overt diabetes as seen in humans." (PMID 41002949, 2025). "Commercial airline pilots with insulin-treated diabetes granted a class 1 medical certificate and private pilots granted a class 2 medical certificate or a light aircraft pilot license (LAPL) must adhere to this protocol." (PMID 39496965, 2025). "The following variables met this threshold: age, BMI at OGTT, family history of diabetes, smoking, fasting insulin, HOMA-IR, fasting triglycerides and TyG index." (PMID 41225974, 2025). "Oxidative stress has been shown to impair two major mechanisms that fail during diabetes: insulin production by the pancreatic β-cells and tissue-specific insulin signaling." (PMID 40700116, 2025). "Current applications include successful delivery of insulin, vaccines (e.g., influenza and rabies vaccines), antifungal agents, and local anesthetics, with emerging potential in diabetes glucose monitoring and cancer immunotherapy." (PMID 40641999, 2025). "Diabetes is a chronic metabolic disorder characterized by hyperglycemia due to insufficient insulin production, change in insulin action or a combination of both." (PMID 40143138, 2025). "Inconsistent accounting for medications used by people with diabetes, including insulin and other glucose-lowering agents, limits the assessment of their impact on POE risk." (PMID 40072731, 2025). "Second, HL enhances functional engagement with diabetes-related technologies, such as continuous glucose monitors and insulin pumps, facilitating more accurate data interpretation and responsive self-management." (PMID 40566297, 2025). "If the insulin signaling pathway of patients with diabetes or insulin resistance is damaged, the effect of exercise training will be greatly affected." (PMID 40362436, 2025). "PTP1B knockout (KO) mice show resistance to obesity and diabetes due to enhanced insulin sensitivity." (PMID 40027018, 2025). "Type 2 diabetes (T2DM) is a common form of diabetes characterized by high blood sugar levels due to reduced insulin sensitivity and secretion, often influenced by lifestyle factors." (PMID 40142957, 2025). "In dogs with diabetes receiving insulin, a diet high in insoluble fiber lowered blood glucose concentrations over time, as well as peak blood glucose concentration (Kimmel at al., 2000)." (PMID 40051530, 2025). "By mitigating oxidative stress, plant-derived antioxidants safeguard pancreatic β-cell integrity, enhance insulin signaling, and attenuate the development of diabetes-related complications, including retinopathy, nephropathy, and cardiovascular disease." (PMID 40563357, 2025). "In this context, advanced oral insulin formulations can improve medication adherence in patients with diabetes and enhance their quality of life." (PMID 39815320, 2025). "This ectopic pancreatic fat accumulation can impair both endocrine and exocrine functions, disrupt hormonal signalling pathways such as insulin resistance and incretin hormone activity, and accelerate the progression from prediabetes to overt diabetes." (PMID 41542178, 2025). "It is primarily known for its role in modulating insulin secretion and influencing glucose metabolism and acts as a precursor for insulin secretion, which has made it a subject of study in diabetes management." (PMID 40083886, 2025). "We also addressed secondary complications: insulin therapy for diabetes, hormone replacement for hypogonadism, and calcium/vitamin D for bone support." (PMID 40979821, 2025). "JAK-STAT pathway is dysregulated in the context of obesity and metabolic disease, moreover, JAK-STAT related proteins was involved in the insulin cascade response and considered as the treatment of obesity and diabetes." (PMID 39891057, 2025).
diabetes (continued). "Diabetes mellitus is a heterogeneous metabolic disorder characterized by chronic hyperglycemia resulting from impaired insulin secretion, defective insulin action, or a combination of both." (PMID 41614828, 2025). "Chronic stress elevates cortisol levels, potentially impacting insulin sensitivity and promoting diabetes onset." (PMID 40437450, 2025). "Diabetes mellitus (DM) is a chronic metabolic disease characterized by persistent hyperglycemia and impaired pancreatic β-cell function and/or insulin resistance, with systemic consequences at the vascular, renal, hepatic, and nervous levels." (PMID 41465463, 2025). "Research indicates that PCs modulate islet fibrosis, enhance pancreatic β-cell function and morphology, and promote insulin release in Wistar rats with high-fat-diet-induced diabetes." (PMID 39995417, 2025). "When cells in the body are unable to utilize insulin as intended, they develop this kind of diabetes." (PMID 40062236, 2025). "Similar to GLP1-RAs, E2 has been shown to prevent the exacerbation of diabetes by improving glucose-stimulated insulin secretion in a prediabetic mouse model, probably through GLP-1-mediated regulation." (PMID 40299427, 2025). "At the same time, increased BPb concentration will damage insulin secretion after meals, leading to increased blood sugar after meals and exacerbating diabetes." (PMID 39932979, 2025). "To tackle these problems, we leveraged a four-dimensional longitudinal T2D dataset from SWNA and developed a series of obesity-diabetes models incorporating different biological mechanisms and assumptions regarding the glucose-insulin regulatory system." (PMID 40568093, 2025). "Participants were considered to have diabetes if they answered “yes” to having diabetes, used glucose-lowering drugs or insulin, or had glycosylated hemoglobin (≥6.5%) and fasting blood glucose (≥126 mg/dl) values indicating diabetes." (PMID 40040693, 2025). "Diabetes mellitus (DM) is a metabolic disorder characterized by high blood sugar levels due to insufficient insulin production or insulin resistance." (PMID 40144552, 2025). "Two significant advantages of this effect are its role in preserving insulin sensitivity and supporting impaired metabolic processes in conditions such as diabetes." (PMID 40918166, 2025). "Because of failed induction of labor (for gestational insulin-requiring diabetes), she underwent cesarean section at 39 weeks of pregnancy and gave birth to a healthy boy with no maternal or neonatal complications." (PMID 41201503, 2025). "Probiotics were found to lower blood glucose and insulin levels in diabetes in preclinical settings as well as clinical trials in humans." (PMID 40422866, 2025). "Diabetes mellitus is a multifactorial metabolic disorder characterized by chronic hyperglycemia resulting from defects in insulin secretion, insulin action, or both." (PMID 40563357, 2025). "Exosomal miRNAs are emerging as key regulators in the development of diabetes mellitus, primarily in terms of insulin resistance and pancreatic β-cell damage." (PMID 41306568, 2025). "Oral microorganisms contribute to systemic inflammation through the secretion of pro-inflammatory cytokines and lipopolysaccharides (LPS), leading to reduced insulin sensitivity and exacerbating diabetes progression." (PMID 40437450, 2025). "This study also addresses how insulin sensitizers have influence over the neuroinflammatory pathways and it bridges the knowledge gap between the metabolic diseases like diabetes mellitus and neurodegeneration." (PMID 40771585, 2025). "Diabetes mellitus is characterized as a chronic metabolic disorder manifested through sustained hyperglycemia, resulting from defective insulin secretion, impaired cellular insulin response, or a combination of these pathophysiological mechanisms." (PMID 40648562, 2025).
diabetes (continued). "While it remains acceptable in people with diabetes receiving subcutaneous insulin therapy and people with insulinoma, it appears to be inaccurate for glucose monitoring during ITT." (PMID 41448958, 2025). "People with diabetes in low- and middle-income countries (LMICs) often face challenges managing their condition with insulin, including difficulties with storage, monitoring blood sugar, and the risk of dangerously low blood sugar levels." (PMID 40245017, 2025). "All five studies excluded women treated with insulin, and four excluded women using other oral diabetes therapies for managing GDM." (PMID 40719094, 2025). "Cigarette smoking was found to be responsible for reduced insulin sensitivity and insulin resistance, worsening the control of blood glucose and leading to diabetes." (PMID 40249027, 2025). "Where PWDI brought information about their current diabetes plan, insulin regimen and monitoring records to hospital there was opportunity for the safe transfer of information to secondary care staff." (PMID 40324886, 2025). "While we were unable to consider additional factors such as family history of diabetes, diet, or insulin sensitivity in the current study, we acknowledge their potential influence on GDM risk." (PMID 40077656, 2025). "Inflammatory cytokines, such as TNF-α and IL-6, are elevated in diabetes and exert inhibitory effects on insulin signaling pathways, thereby perpetuating insulin resistance." (PMID 40280905, 2025). "Diabetes mellitus presents two fundamental pathological characteristics including insulin resistance and β‐cell dysfunction." (PMID 41268687, 2025). "Diabetes Mellitus with elevated insulin levels increases inflammation and cell apoptosis, decreasing healing factors post-surgery." (PMID 40519247, 2025). "Diabetes mellitus (DM) is a metabolic disease characterized by hyperglycemia, resulting from either insufficient insulin secretion, an impairment in insulin functionality, or both." (PMID 40244213, 2025). "Carers’ roles can range from simple emotional support, such as providing company or help in daily activities, to diabetes-specific medical care, such as the administration of medications including insulin injections and regular blood glucose monitoring." (PMID 40863223, 2025). "This includes inflammation driven by the inflammasome effector cytokine IL‐1β within plaque‐laden arterial walls during atherosclerosis and the impairment of insulin signaling during diabetes." (PMID 39327931, 2025). "In this report, NPH insulin was selected as the initial treatment for diabetes resulting from a PTF1A enhancer mutation, following established neonatal diabetes protocols." (PMID 40443916, 2025). "Most patients had a family history of diabetes (92.9%) and had received a range of therapies including insulin (50%)." (PMID 40148250, 2025). "The results showed that nine indexes, including age, BMI, Diabetes course, Insulin therapy, Hypertension, HbA1c, TC, HDL, and TyG, were retained, and five indexes (sex, smoking, drinking, FBG, and LDL) were excluded." (PMID 41293734, 2025). "Among seventeen patients who are presently in-patients of the spinal unit and positive for vancomycin-resistant Enterococcus, six have diabetes mellitus (35%) and five of these patients have been taking insulin." (PMID 41156718, 2025). "The analysis was stratified by age, sex, BMI, diabetes duration, oral antidiabetic medication use, insulin use, and HbA1c level." (PMID 40432216, 2025). "Genetic polymorphisms, especially those that influence mitochondrial functionality and insulin signaling mechanisms, are integral to the etiology of diabetes." (PMID 40862129, 2025). "A combined protocol of HIIT and resistance training effectively improved insulin sensitivity and HbA1c levels in individuals with type 2 diabetes mellitus." (PMID 41295324, 2025).
diabetes (continued). "Diabetes mellitus (DM) is a heterogeneous metabolic disorder characterized by chronic hyperglycemia, arising from insufficient insulin secretion and/or utilization due to multifactorial etiologies." (PMID 40508108, 2025). "Firstly, GLP‐1RAs have been shown to enhance insulin sensitivity, which is particularly relevant in the context of diabetes‐related ocular complications." (PMID 40509955, 2025). "Silver nanoparticles due to their smaller sizes enter into the cell and enhance their capability to produce more insulin to eliminate diabetes." (PMID 40585503, 2025). "Orexin is a promising therapeutic target for the management of insulin resistance and diabetes because of its function in regulating peripheral glucose uptake throughout tissues, hepatic glucose synthesis, and insulin secretion." (PMID 41438219, 2025). "Diabetes mellitus (DM) is a metabolic disorder characterized by inadequate insulin production or abnormal insulin response, resulting in high blood sugar (glucose) levels." (PMID 40489503, 2025). "The build-up of lipid droplets within pancreatic islets disrupts glucose-induced insulin release, leading to diabetes onset." (PMID 40917348, 2025). "Type 2 diabetes mellitus (T2DM) is primarily characterized by persistent hyperglycemia, a relative deficiency in insulin secretion, and resistance, resulting in dysregulated glucose homeostasis." (PMID 41227734, 2025). "The evidence presented with DAVOS shows that ESYSTA leads to improved blood glucose control in people with diabetes treated with insulin." (PMID 40661654, 2025). "Shortages of insulin impair diabetes management, increasing the likelihood of severe complications, including kidney failure, cardiovascular disease, vision loss, and diabetic foot amputation." (PMID 41343509, 2025). "Diabetes self-management requires daily glucose monitoring, insulin administration, personalized nutrition, and physical activity, which become challenging for adolescents balancing competing priorities including studies, social life, and paid employment." (PMID 40599715, 2025). "Diabetes-related oxidative stress contributes to the injury of various kinds of cells, and impairs both insulin secretion and action." (PMID 40806520, 2025). "According to data from a survey on the care situation of people diagnosed with diabetes in 2021/2022, a total of 87.5 % of adults aged 45 and over with type 2 diabetes are dependent on treatment with insulin or other antidiabetic drugs." (PMID 41030674, 2025). "As we know, in some types of diabetes (particularly type 1 diabetes and some autoimmune β-cell damage), immune cells attack the insulin-producing cells (β-cells) of the pancreas." (PMID 41465308, 2025). "Although the number of individuals with diabetes-related osteoporosis is increasing year on year, the common drugs on the market remain insulin, bisphosphonates, and raloxifene, the use of which has been reported to induce adverse side effects." (PMID 40243576, 2025). "In light of its crucial role in regulating blood glucose levels, α-amylase inhibition has emerged as a promising strategy for managing diabetes mellitus (DM), particularly type II DM, which is marked by impaired glucose metabolism and insulin resistance." (PMID 40971374, 2025). "In endocrine irAEs, hormone replacement or disease-specific therapy was the mainstay: levothyroxine for hypothyroidism, insulin or oral hypoglycemics for diabetes, carbimazole for hyperthyroidism, and fluid restriction for hyponatremia or SIADH." (PMID 41235221, 2025). "Diabetes mellitus is a chronic metabolic disorder characterized by abnormal blood glucose levels due to insufficient insulin production or improper insulin utilization." (PMID 41345203, 2025). "Sulfonylureas have emerged as a novel therapeutic strategy in controlling diabetes and COVID-19 infection, effectively addressing central insulin resistance and improving arterial stiffness, particularly in cancer patients." (PMID 40599143, 2025).